LCORL (ligand dependent nuclear receptor corepressor like)
Description:
May act as transcription activator that binds DNA elements with the sequence 5'-CCCTATCGATCGATCTCTACCT-3'. May play a role in spermatogenesis (By similarity).
Synonyms: MLR1; FLJ30696
Tractability: PROTAC: UniProt records ubiquitination sites on it; ubiquitination databases record sites on it.
Gene: Protein-coding gene on chromosome 4 (17,841,187 to 18,021,993, reverse strand). Ensembl gene ENSG00000178177.
Subcellular location: Nucleus
Subcellular location (Human Protein Atlas): Nucleoplasm; Nuclear membrane
Gene Ontology:
Molecular function: histone methyltransferase binding; protein binding; DNA binding
Biological process: regulation of transcription by RNA polymerase II
Cellular component: nucleus
Genetic constraint (gnomAD): Loss-of-function variants: 30 observed, 119.15 expected, observed/expected ratio (o/e) 0.25, 90% interval 0.19 to 0.34. The synonymous counts are far from expectation, so gnomAD's model fits this gene poorly and the ratio says little. Missense variants: 1,609 observed, 1,955.9 expected, observed/expected ratio (o/e) 0.82, 90% interval 0.79 to 0.86. Synonymous variants: 552 observed, 672.4 expected, observed/expected ratio (o/e) 0.82, 90% interval 0.76 to 0.88.
Homologues: Orthologues: chimpanzee LCORL (99% identical), macaque LCORL (96% identical), pig LCORL (83% identical), rabbit LCORL (83% identical), dog LCORL (82% identical), mouse Lcorl (71% identical). Paralogues in human: LCOR (13% identical).
Diseases named in the same sentence as LCORL in open-access papers:
LCORL is named in the same sentence as 11 diseases in open-access papers, as found by Europe PMC text mining. Sharing a sentence is not in itself a finding about the gene and the disease. The quoted sentences say what the papers report.
asthma (1 paper, 2021). "Conversely, genetic variants upstream of ligand-dependent nuclear receptor corepressor-like gene (LCORL), previously involved in height determination and spermatogenesis, were associated with asthma only in males (minimum p = 5.31 × 10−8 for rs4593128)." (PMID 34834492, 2021). "Variants upstream LCORL gene had a sex-specific involvement in male asthma susceptibility." (PMID 34834492, 2021). "Four variants near lactate dehydrogenase A pseudogene 3 (LDHAP3) on 2p21 and 90 variants upstream of the ligand dependent nuclear receptor corepressor-like (LCORL) gene on region 4p15.31 were suggestively associated with asthma, five of them reaching the genome-wide significance." (PMID 34834492, 2021).
salivary gland neoplasm (1 paper, 2017). Tumors of the SALIVARY GLANDS. "The LCORL protein is a transcription factor implicated in humans in effects on skeletal size and adult height; PLAG1 is developmentally regulated, often associated with salivary gland neoplasms, and has been linked with growth rates in cattle." (PMID 28219344, 2017).
squamous cell carcinoma (1 paper, 2021). A carcinoma arising from squamous epithelial cells. "Genetic variants in LCORL have been associated with familiar squamous cell carcinoma and with biometric variables, such as birth weight and height in different stages of life (fetal growth, childhood, and adulthood)." (PMID 34834492, 2021).
Stillbirth (1 paper, 2015). Death of the fetus in utero after at least 22 weeks of gestation. "We then identified two well-known genes, NCAPG and its near neighbor LCORL within 37.2–37.5Mb on OAR6, which are reported to be involved in fetal growth, stillbirth, and carcass size in sheep and other livestock." (PMID 26083354, 2015).
tumor (1 paper, 2021). "The comparison of gene expressions in tumor and normal tissues revealed that CTSG and LCORL were downregulated, while TNFRSF4 and PLAU were upregulated in OSCC tissues." (PMID 34497859, 2021).
LCORL also shares sentences with these, for which no sentence is quoted: depression (1 paper); Hip dysplasia (1); metastatic diseases (1); Obesity (1); psoriasis (1); type 2 diabetes (1).